EZH2 (enhancer of zeste 2 polycomb repressive complex 2 subunit)
Diseases named in the same sentence as EZH2 in open-access papers (continued):
Sharing a sentence is not in itself a finding about the gene and the disease.
cancer (continued). "Enhancer of zeste homolog 2 (EZH2) is a member of the polycomb group complex and plays an important role in the proliferation and metastasis of various cancers via methylation of histone H3K27." (PMID 30544763, 2018). "Enhancer of zeste homolog 2 (EZH2) is a histone lysine N-methyltransferase involved in the PRC2 (Polycomb Repressive Complex 2), which has been widely studied in cancer including MB." (PMID 30560106, 2018). "This review highlights the paradoxical functions of EZH2 and KDM6B during EMT and cancer aggressiveness." (PMID 34991274, 2018). "EZH2 overexpression therefore led to the activation of the Wnt/β-CATENIN pathway that favored liver tumor initiating cells (TIC) self-renewal and cancer aggressiveness." (PMID 34991274, 2018). "EZH2-catalyzed tri-methylation of H3K27 induces the suppression of gene expression and is correlated with the onset and development of various types of cancer." (PMID 30558227, 2018). "As in other cancer types, MALAT1 was found to interact with the methyltransferase EZH2 also in MM cells, and both MALAT1 and EZH2 inhibitors reduced H3K27Me3 at KEAP1 promoter, thus upregulating KEAP1 mRNA." (PMID 29487387, 2018). "Correlation analysis of the dataset GSE76297 (92 pairs of cancer and 91 normal tissue samples) from the Molecular Signature Database suggested that CDKN1A was substantially negatively correlated with EZH2 and SNHG1." (PMID 29970899, 2018). "Small molecule inhibitors targeting EZH2 and other H3K27 methyltransferases are effective treatments for various types of cancers, as they promote a reduction in H3K27me3 leading to cell cycle arrest and increased apoptosis." (PMID 29710783, 2018). "The development of highly selective inhibitors against the histone methyltransferase activity of EZH2 has also contributed to insight into the role of EZH2 and PRC2 in tumorigenesis, and their potential as therapeutic targets in cancer." (PMID 30761216, 2018). "An aberrant situation was found in cancer, where H3K27me3 and HMGA are both present; in this case, EZH2/H3K27me3 inhibitors have been suggested as anticancer therapeutic agents." (PMID 29853899, 2018). "With regard to the potential effectors of the distinct chromatin signatures, enrichment analyses of transcription factors revealed the presence of EZH2 and SUZ12 polycomb components at DNA hypermethylated sites, both in cancer and aging." (PMID 29504244, 2018). "EZH2 knockdown in colon (DLD‐1, HT‐29) and breast (HCC‐1806, 4T‐1) cancer cells result in compromised CSC properties in‐vitro (spheroid formation and drug resistance) and in‐vivo (tumorigenic potential) as compared to control cells." (PMID 29460395, 2018). "This is an important point since inhibition of chromatin regulators such as EZH2, DOT1L and LSD1, which also exist in stable multi-protein complexes is currently under clinical investigation in several cancers." (PMID 30431433, 2018). "For example, gain-of-function mutations in EZH2, EED or SUZ12 occur in multiple cancer types, and both EZH2 and EED are current targets for cancer therapy." (PMID 30005706, 2018). "Taken together these results suggest that MC2884 modulates the epigenome through inhibition of EZH2 and HAT actions in the low μM range giving rise to decreased histone acetylation and H3K27me3 in different cancer cell lines." (PMID 29876013, 2018). "Moreover, we discuss a variety of agents targeting EZH2 that may improve cancer treatment." (PMID 28415635, 2017). "With this study, we tested the biological activity of the catalytic EZH2 inhibitor MC3629, designed and prepared by us as a simplified analog of EPZ005687 and GSK2816126, in the SHH MB cancers cells and SLCs." (PMID 28978137, 2017). "EZH2 expression was significantly higher in the UAMS molecularly defined PR subgroup, which is characterised by the overexpression of cancer-testis antigens, cell cycle and proliferation-related genes, and was significantly higher in GEP70 high-risk patients." (PMID 28362441, 2017).
cancer (continued). "We recorded overexpression of cancer related genes including ALK, CDKN2A, and EZH2 compared with normal skin." (PMID 28359267, 2017). "MiRNA-124 plays a key role in cancer cell proliferation and is epigenetically silenced in various types of cancers, and affects proliferation and motility of cancer cells by repressing ROCK2 and EZH2." (PMID 29073265, 2017). "Coexistence of enhancer of zeste homolog 2 (EZH2) and BRAF gene aberrations has been described in many cancer types." (PMID 29202777, 2017). "For example, the methyltransferase enhancer of zeste homolog 2 (EZH2) and its substrate (H3K27 methylation) is overexpressed in numerous cancer types and is frequently indicative of a poor prognosis." (PMID 28143553, 2017). "EZH2, a HMT contributor to PRC2, is overexpressed in a variety of human cancers including those that express high MYC levels." (PMID 28505071, 2017). "Both of them have been reported to interact with enhancer of zeste homolog 2 (EZH2), which also functions as a H3K27 methyltransferase when part of PRC2, to epigenetically inhibit genes responsible for suppressing cancer development, and increase metastasis." (PMID 27992370, 2017). "Based on the EZH2 role in tumorigenesis and stem cell maintenance, studies have been focused on targeting EZH2, a H3K27 methyltransferase, as a novel cancer treatment, and aimed to identify small molecules that inhibit its catalytic activity." (PMID 28978137, 2017). "It has been shown that various lncRNAs, such as LINC00511 or XIST, served as a modular scaffold of EZH2/PRC2 complexes and interacted and coordinated their localization, thereby contributing to cancer progression." (PMID 29228709, 2017). "The methyltransferase enhancer of zeste homolog 2 (EZH2), is the core catalytic element of polycomb repressive complex 2 (PRC2), and plays an important role in the regulation of cancer initiation, progression, invasion, and drug resistance." (PMID 29221202, 2017). "Notably, prior work has suggested thatBAP1, PBRM1, and ARID1Adeficiency all result in sensitivity to EZH2 inhibition across cancer types; the association of ARID1Amethylation with IDH mutation opens the question of whether EZH2 inhibition mightalso be effective in this subtype." (PMID 28297679, 2017). "EZH2- and DNMT1-mediated epigenetic regulation contributed to the growth and progression of different cancer cells." (PMID 28360411, 2017). "Furthermore, from the RegulomeDB database 31, data suggest that rs531564 is likely to affect the binding of a transcriptional factor called EZH2, which is involved in chromatin remodeling and gene silencing in cancer, and may alter the aggressiveness of tumors and their progression." (PMID 28074552, 2017). "The six selected genes (TWIST1, LAMB1, THY1, EZH2, SALL4, and TCF3) are involved in cell differentiation, HCC cancer stem cells (CSCs) markers, and CSCs involved pathways." (PMID 28158312, 2017). "Moreover, EZH2 is often upregulated in various cancers and the expression of EZH2 often correlates with poor patient outcome; although this could, at least in some cases, be simply reflecting the higher proliferative phenotype associated with cancer progression." (PMID 27756687, 2017). "Therefore, it is hypothesized that EZH2 promotes cancer initiation by blocking differentiation." (PMID 28410242, 2017). "Thus, the bone microenvironment may favour reduced EZH2 activities in cancer cells." (PMID 28429794, 2017). "MiR-101 exercises its biological function in multiple cancer types by interating with CXCR7, CDK8, EZH2 level and CPEB1." (PMID 27911279, 2017). "For example, EZH2 was shown to methylate and competitively inhibit the ubiquitination of H2BK120, which is a lysine residue, in cancer cells." (PMID 28418882, 2017).
cancer (continued). "Overall, in this study we validated EZH2 as an attractive target for SHH MB cancer and cancer stem cell impairment, and showed that EZH2 pharmacological inhibition exerted by MC3629 is effective in MB cells and in MB xenografted mouse models." (PMID 28978137, 2017). "The present studies demonstrate that MUC1-C drives EZH2 expression in TNBC, NSCLC and other types of carcinoma cells." (PMID 28785086, 2017). "TIMPs have been shown to be regulated by histone modification enzymes, such as EZH2 and TET1, in cancer." (PMID 27058897, 2016). "However, the regulation of EZH2 activity by tumor suppressor kinase in cancer remains unclear." (PMID 27494834, 2016). "Enhancer of Zeste Homolog 2 (EZH2), the core catalytic component of the polycomb repressive complex 2 (PRC2), also affects cancer progression by altering histone H3lysine27 (H3K27) trimethylation and silencing transcription." (PMID 26799422, 2016). "High expression of polycomb group protein enhancer of zeste homologue 2 (EZH2), a key component of the polycomb PRC2 complex, links to aggressive cancer progression." (PMID 27172794, 2016). "It is possible that cancer cells with ALT rely on PRC2 function, and that therefore inactivation of both ATRX and EZH2 is synthetic lethal in CRC." (PMID 27634879, 2016). "DZNeP downregulates EZH2, reactivates several tumor suppressor genes inhibited by polycomb repressive complex 2 (PRC2), and inhibits cancer cell phenotype." (PMID 27651838, 2016). "Various cancers have been studied in relation to a large number of KMTs that include MMSET, EZH2, and MLL family members." (PMID 27119045, 2016). "The method’s utility is highlighted by some well-known cancer genes such as CDK4, APC and EZH2 are only captured by GAP." (PMID 27296290, 2016). "Enhancer of zeste 2 (EZH2), a key component of polycomb repressive complex 2 (PRC2), was of great importance in human cancer pathogenesis." (PMID 26859127, 2016). "Therefore, inhibition of EZH2 through direct and indirect mechanisms, such as epigenetic activation of oncogenic signaling cascades and silencing of tumor suppressor genes, could be an important approach for cancer treatment." (PMID 27421653, 2016). "DZNep, an S-adenosylhomocysteine (SAH) hydrolase inhibitor, has been characterized as an EZH2 inhibitor that disrupts PRC2 and manifests antitumor activity in a variety of cancers." (PMID 27472460, 2016). "EZH2 inhibitors GlaxoSmithKline-126 (GSK-126) and 3-deazaneplanocin-A reduced AR-transcriptional activity, leading to the inhibition of cancer cells self-renewal mechanisms, tumorigenesis, and metastasis mediated by aberrant EZH2 upregulation in PCa cells." (PMID 27891254, 2016). "A series of EZH2-specific small molecule inhibitors including GSK126, GSK343 and GSK503 have been developed recently by GlaxoSmithKline and their effective anti-cancer activity has been demonstrated in various cancer models." (PMID 26657505, 2016). "Given that approximately 20% of human cancer has alterations in SWI/SNF, there is growing interest in EZH2 as a therapeutic target." (PMID 27242978, 2016). "We compared the mRNA expression level of MALAT1 and Ezh2 in ESCC cancer tissues and found that there was remarkably positive correlation between MALAT1 and Ezh2 expression (P<0.0001)." (PMID 27015363, 2016). "In this review, we describe those enzymes and their inhibitors that have already reached the first stages of clinical trials in cancer therapy, namely the histone methyltransferases DOT1L and EZH2 as well as the demethylase LSD1." (PMID 27222667, 2016).
cancer (continued). "Our MTT assays over a 4-day time course showed that individual knockdown of H1.2 and EZH2 in MCF7, LD611 and LNCaP cancer cells gradually decreased cell proliferation rates." (PMID 26581166, 2015). "This is in line with the activating effect that EZH2 induces on the NOTCH1 gene, which triggers the expansion of cancer stem cells through a repressive-independent mechanism." (PMID 26029238, 2015). "To functionally investigate the observed changes in cancer cells, we purified total RNA from MCF7 cells expressing shRNAs against H1.2 and EZH2, and conducted microarray analyses using the Illumina humanHT-12 v4 Expression BeadChip arrays." (PMID 26581166, 2015). "The oncoprotein EZH2, as a histone H3K27 methyltransferase, is frequently overexpressed in various cancer types." (PMID 26484567, 2015). "Protein levels of EZH2 in Karpas-422 and SUDHL4 lines were similar to that present in other cancer cell lines." (PMID 25605023, 2015). "Recently, a number of EZH2 targets including E-cadherin, RUNX3, STAT3 and various EZH2 interacting proteins including Jarid2 and PHF1 have been found to mediate EZH2-regulated cancer progression." (PMID 26038315, 2015). "The pharmacologic inhibition of EZH2 has been shown by several agents, including 3-Deazaneplanocin A (DZNep), sulforaphane, and GSK126 to show anti-cancer activities in vitro and in vivo." (PMID 25431950, 2014). "The expression levels of miRs complementary to EZH2 and MFGE8 mRNA and cancer malignancies were evaluated." (PMID 25081869, 2014). "In contrast, among 10 tumors (#1-10) from the same set of samples, the mRNA expression of its targets (EZH2, MCL-1 and FOS) was significantly higher in cancer tissues." (PMID 25153722, 2014). "Enhancer of zeste homolog 2 (EZH2) enhances tumorigenesis and is commonly overexpressed in several types of cancer." (PMID 24861464, 2014). "For instance, EZH2 and UHRF1 are two of the most frequently overexpressed chromatin factors but are rarely amplified in cancer." (PMID 25484917, 2014). "Deazaneplanocin A (DZNep), a S-adenosyl-L-homocysteine hydrolase inhibitor, targets enhancer of zest homolog 2 (EZH2), a component of polycomb repressive complex 2 (PRC2) and is capable to induce the death of cancer cells." (PMID 25255316, 2014). "Enhancer of zeste homolog 2 (EZH2), a key protein in the PRC2 complex, was also found to have prognostic value in several types of cancer." (PMID 25243792, 2014). "We further showed inactivation of EZH2 by 3-Deazaneplanocin A (DZNep) that re-expressed DLC1 and remarkably abolished cytoskeletal reorganization and inhibited cell migration in cancer cells." (PMID 23826380, 2013). "Further studies are needed to elucidate the mechanisms for the mutual exclusiveness of EZH2 and HDAC4 and to determine therapeutic targets for the distinct epigenetic-specific cancer phenotypes." (PMID 24079712, 2013). "EZH2 activation and HDAC4 activation correlate with growth factor signaling and inflammation, respectively, and represent two distinct states for cancer cells." (PMID 24079712, 2013). "Enhancer of Zeste homolog 2 (EZH2), the catalytic subunit of the Polycomb repressive complex 2 (PRC2), is frequently overexpressed in various cancers." (PMID 24266940, 2013). "Enhancer of zeste homolog 2 (EZH2) is a methyltransferase that specifically mediates histone H3K27 methylation and has been found to be deregulated in a variety of cancer types." (PMID 24028781, 2013). "Consistent with the findings from human HCC, concomitant DLC1 down-regulation and EZH2 up-regulation was observed in these malignancies, suggesting the implications of EZH2 up-regulation in silencing DLC1 expression in different human cancers." (PMID 23826380, 2013). "As we previously discussed, several epigenetic modifiers such as EZH2, IDH1/2, and DNMT3A are genetically altered in cancer." (PMID 23533770, 2013).
cancer (continued). "Previous studies in cancer and stem cells suggest that HDAC inhibition suppresses transcription of polycomb proteins and results in a depletion of EZH2." (PMID 23077658, 2012). "The transcription levels of the two H3K27 demethylase genes, UTX and JMJD3, the H3K27 methyltransferase EZH2 and the CDK4/CDK6 inhibitor p16INK4a were determined by qRT-PCR in cancer tissues and adjacent normal tissues from 36 RCC patients." (PMID 23057811, 2012). "Levels of UTX and JMJD3 proteins were obviously increased in cancer tissues compared to adjacent normal tissues, while the level of H3K27me3 was reduced and H3K27 methyltransferase EZH2 was upregulated." (PMID 23057811, 2012). "Significantly, EZH2 has been reported to play a key role in mediating both histone methylation and DNA methylation of HOXB13 gene in some cancer cells." (PMID 22808286, 2012). "The level of tri-methylated H3K27 (H3K27me3) was lower in cancer tissues compared to normal tissues, but expression of the H3K27 methyltransferase EZH2 was increased (P < 0.05)." (PMID 23057811, 2012). "We acquired expression data for KDM5A targets and EZH2 targets from the GSK dataset and applied z-score analysis to study the significance of their combined up- or downregulation in different cancer cell lines samples." (PMID 21886846, 2011). "In fact, EZH2 and STEAP express in very low amounts in normal tissues and benign neoplasms and upregulated and overexpressed in malignant tumors." (PMID 22053850, 2011). "The histone methyl transferase EZH2, a specific H3K27 methyl transferase, is frequently over-expressed in human cancer." (PMID 22110741, 2011). "MLL, another H3K4 methyltransferase, is frequently translocated in various forms of leukaemia and the polycomb protein EZH2, a H3K27 specific histone methyl-transferase, is altered in multiple types of cancer." (PMID 22011431, 2011). "Recently, MYC protein recruited the PRC2/EZH2/DNMT3B complex to bind to the RASSF1A promoter, which led to RASSF1A gene silencing by promoter CpGs hypermethylation and condensed chromatin in cancer cell." (PMID 20877461, 2010). "We were particularly interested in miR-101 since it was confirmed to bind the EZH2 3’-UTR at two sites, and was recently shown to interact with EZH2 in other types of cancer." (PMID 21321380, 2010). "EZH2 is overexpressed and correlates with poor prognosis in many cancers, however, the status of H3K27 methylation and its clinical implication in cancer patients are rarely studied." (PMID 20028503, 2009). "Based on their role in stem cells, EZH2 and BMI1 have been predicted to contribute to a poor outcome for cancer patients." (PMID 19099573, 2008). "Furthermore, via its interaction with EZH2, CCAT2 inhibits the production of p15 in cancer of the breast cells." (PMID 41459628, 2026). "The sensitivity of cancer cells actively expressing both NRF1 and EZH2 to EZH2i is significantly greater than that of cancer cells actively expressing individual EZH2 or NRF1 alone and much greater than that of cancer cells expressing low levels of EZH2 and NRF1." (PMID 42140904, 2026). "As EZH2 and MYC were dysregulated in a range of human tumors, we sought to determine whether squamocin can effectively degrade both EZH2 and MYC in other types of cancer." (PMID 39823459, 2025). "Pathologically, an upregulation of EZH2, as observed in many different types of cancers, can essentially contribute to chemoresistance of CRC virtually through promoting cancer stem cell maintenance by modulating major intestinal stem cell renewal pathways such as Wnt/β-catenin and Hedgehog." (PMID 39851496, 2025).